ZNF714 (zinc finger protein 714)
Description:
May be involved in transcriptional regulation.
Gene: Protein-coding gene on chromosome 19 (21,077,069 to 21,125,270, forward strand). Ensembl gene ENSG00000160352.
Subcellular location: Nucleus
Pathways (Reactome):
Gene expression (Transcription): Generic Transcription Pathway
Genetic constraint (gnomAD): Loss-of-function variants: 28 observed, 41.49 expected, observed/expected ratio (o/e) 0.67, 90% interval 0.5 to 0.93. The upper end of that interval is the gene's LOEUF score, 0.93, which puts it in group 3 of 6, group 1 being the genes least tolerant of losing a copy. Missense variants: 589 observed, 605.31 expected, observed/expected ratio (o/e) 0.97, 90% interval 0.91 to 1.04. Synonymous variants: 183 observed, 194.56 expected, observed/expected ratio (o/e) 0.94, 90% interval 0.83 to 1.06.
Homologues: Orthologues: chimpanzee ZNF714 (99% identical). Paralogues in human: ZNF726 (65% identical), ZNF728 (65% identical), ZNF708 (65% identical), ZNF254 (65% identical), ZNF676 (64% identical), ZNF492 (63% identical), ZNF429 (62% identical), ZNF724 (61% identical), ZNF493 (60% identical), ZNF681 (59% identical), ZNF90 (58% identical), ZNF85 (58% identical), and 164 more.
Diseases named in the same sentence as ZNF714 in open-access papers:
ZNF714 is named in the same sentence as 23 diseases in open-access papers, as found by Europe PMC text mining. Sharing a sentence is not in itself a finding about the gene and the disease. The quoted sentences say what the papers report.
breast carcinoma (2 papers, 2019 to 2023). "Finally, these factors (ZNF273, ZNF485, ZNF695, ZNF643, and ZNF789), together with ZNF714, had significantly increased mRNA levels in the DNA methylation cluster 5 identified for breast cancer, which also coincides with the basal‐like subtype and the lowest overall DNA methylation level." (PMID 30444046, 2019). "We also silenced ZNF714 expression in two breast cancer cell lines, namely MDA-MB-468 (basal breast cancer) and MCF7 (luminal A)." (PMID 37958512, 2023).
Insulin resistance (2 papers, 2023 to 2025). Increased resistance towards insulin, that is, diminished effectiveness of insulin in reducing blood glucose levels. "Interestingly, previous reports pointed toward the involvement of ZNF714 in diabetes and insulin resistance." (PMID 37958512, 2023).
adrenocortical carcinoma (1 paper, 2023). "In general, high ZNF714 expression correlated with poorer overall survival in PCPG and mesothelioma (MESO) and disease-free survival in uveal melanoma (UVM), kidney renal papillary cell carcinoma (KIRP), and adrenocortical carcinoma (ACC)." (PMID 37958512, 2023).
breast tumors (1 paper, 2023). "In their analysis, the genomic region harboring ZNF714 (and other genes, including its closest neighbors: ZNF85, ZNF430, ZNF431, ZNF708) was found to undergo copy number gains in estrogen-negative (ER-) breast tumors as compared to ER+ tumors." (PMID 37958512, 2023).
cleft lip (1 paper, 2022). Congenital defect in the upper lip where the maxillary prominence fails to merge with the merged medial nasal prominences. "ZNF714 has been reported to be associated with non-syndromic cleft lip." (PMID 35787786, 2022).
glioblastoma (1 paper, 2023). The most malignant astrocytic tumor (WHO grade IV). "Second, we observed that ZNF714 expression varies among different molecular subtypes in 10 tumor types, including BRCA, ESCA, glioblastoma (GBM), head and neck cancer (HNSC), low-grade glioblastoma (LGG), LIHC, LUSC, ovarian cancer (OV), pheochromocytoma and paraganglioma (PCPG), and UCEC." (PMID 37958512, 2023).
lung carcinoma (1 paper, 2023). "In the last steps of our analyses, we identified a relatively small group of genes whose expression becomes commonly deregulated upon ZNF714 knockdown in both lung cancer cell lines." (PMID 37958512, 2023). "Moreover, ZNF714 expression proved to be significantly upregulated in both major histopathological subtypes of lung cancer, namely LUAD and LUSC." (PMID 37958512, 2023). "Thus, we wanted to explore the cancer-related functions of ZNF714 using TCGA-centered online databases, as well as in vitro phenotypic studies and multi-omic analyses in lung cancer cell line models." (PMID 37958512, 2023). "In conclusion, our results reveal, for the first time, that ZNF714 may support pro-oncogenic features in lung cancer cells." (PMID 37958512, 2023). "The in vitro phenotypic studies in the lung cancer model indicated that ZNF714 may support proliferation, migration, and invasion in a cell-type-dependent manner." (PMID 37958512, 2023). "Furthermore, we asked whether ZNF714 may affect gene expression in both analyzed lung cancer cell lines." (PMID 37958512, 2023).
ovarian carcinoma (1 paper, 2023). A malignant neoplasm originating from the surface ovarian epithelium. "The ZNF714 promoter was also shown to be hypomethylated in monozygotic twins with ovarian cancer compared to their healthy non-twin siblings." (PMID 37958512, 2023).
prediabetes (1 paper, 2025). "Compared to the control group, we detected 130 DMCs that were shared between the prediabetes and T2D groups, with LCLAT1, HLA-C, NINJ2, ZNF714, CNDP2, and HOOK2 among the top differentially methylated genes." (PMID 41373473, 2025). "A total of 130 DMCs across 99 genes, including LCLAT1, HLA-C, ZNF714, and HOOK2, were shared by prediabetes and T2D groups." (PMID 41373473, 2025).
psoriasis (1 paper, 2021). An autoimmune condition characterized by red, well-delineated plaques with silvery scales that are usually on the extensor surfaces and scalp. "Among DMRs identified between “all psoriasis” patients versus healthy controls, skin psoriasis patients versus healthy controls, PsA patients versus healthy controls, and skin psoriasis versus PsA patients with ≥5 CpGs, only 1 DMR within the ZNF714 gene was common to all analyses." (PMID 34746142, 2021).
thyroid carcinoma (1 paper, 2023). "Only thyroid carcinoma (THCA) showed significantly lowered ZNF714 levels." (PMID 37958512, 2023).
type 1 diabetes (1 paper, 2023). "High near-birth ZNF714 expression was incorporated into the predictive model identifying patients at risk of type 1 diabetes." (PMID 37958512, 2023).
cancer (4 papers, 2019 to 2025). A tumor composed of atypical neoplastic, often pleomorphic cells that invade other tissues. "ZNF714 is also strongly associated with the expression of its neighboring genes, further implying the overrepresentation of this locus in cancer samples." (PMID 37958512, 2023). "Additionally, two immunostimulators were associated with ZNF714 expression in a pan-cancer manner, namely, Tumor Necrosis Factor Superfamily Member 15 (TNFSF15) and UL16 Binding Protein, a ligand activating NK and T cells (ULBP1)." (PMID 37958512, 2023). "Furthermore, the pan-cancer data indicated a positive association between ZNF714 mRNA level and the expression of several immunoinhibitors." (PMID 37958512, 2023). "However, a recent multi-modal computational search for driver mutations identified ZNF714 as a putative driver in several cancers, including LUSC." (PMID 37958512, 2023). "Nevertheless, further studies using animal models and other tumor types are needed to better understand the role of ZNF714 in a cancer setting." (PMID 37958512, 2023). "According to the best of our knowledge, this is the first study demonstrating that ZNF714 supports pro-oncogenic features in cancer cell lines." (PMID 37958512, 2023). "We commenced our in-depth analysis of ZNF714’s involvement in cancer biology by exploration of the online tools utilizing TCGA datasets." (PMID 37958512, 2023). "Our observations suggest that the mechanisms driving reduced growth rate in cancer cells upon ZNF714 knockdown are cell-type dependent." (PMID 37958512, 2023). "First, we screened various online tools utilizing TCGA data to explore the status of ZNF714 in a pan-cancer setting." (PMID 37958512, 2023). "Our pan-cancer analyses confirmed frequent ZNF714 overexpression in multiple tumors, possibly due to regional amplification, promoter hypomethylation, and Nuclear Transcription Factor Y Subunit Beta (NFYB) signaling." (PMID 37958512, 2023). "Our following analytical workflow concentrated on other aspects related to the potential molecular alterations of ZNF714 in cancer." (PMID 37958512, 2023). "In their analysis, an increased expression of ZNF714 was found in the spheroids formed by the HCT116 colon cancer cell line, together with other genes associated with a cancer stem cell signature." (PMID 37958512, 2023). "While this is an important observation implying a potential involvement of ZNF714 in cancer, it will be crucial to validate the transcriptomic data at the protein level." (PMID 37958512, 2023). "Here, we harnessed The Cancer Genome Atlas (TCGA)-centered databases and performed functional studies with transcriptomic and methylomic profiling to explore ZNF714 function in cancer." (PMID 37958512, 2023). "Future studies should focus on ZNF714 protein expression in a pan-cancer setting." (PMID 37958512, 2023). "Thus, to further investigate the function of ZNF714 in cancer, we performed a series of gold-standard phenotypic in vitro assays aiming to explore the ZNF714 effect on proliferation, apoptosis, cell cycle, migration, and invasion." (PMID 37958512, 2023). "Next, we asked about the potential mechanisms triggering ZNF714 overexpression in cancer." (PMID 37958512, 2023). "ZNF714 is a gene with an unknown role in cancer and sparse literature reports about its molecular function." (PMID 37958512, 2023). "Moreover, the cancers with high ZNF714 levels exhibited low interactions with the immune system." (PMID 37958512, 2023). "Interestingly, cancer‐related upregulation of ZNF695, ZNF714, and ZNF138 mirrors the differential expression observed between pluripotent stem cells and differentiated cells." (PMID 30444046, 2019).
tumor (3 papers, 2019 to 2025). "This signature indicates an association between ZNF714 level and humoral response within tumor tissue." (PMID 37958512, 2023). "As stemness is an important aspect of tumor biology supporting metastatic events and therapy resistance, we speculated that ZNF714 association with stem cell phenotype may also be related to carcinogenesis." (PMID 37958512, 2023). "We also showed that ZNF714 expression was associated with molecular subtypes in many tumor types (10 out of 17), whereas the association with patient prognosis, tumor stage, and grade was rare." (PMID 37958512, 2023). "As ZNF714 expression was previously shown to increase in induced pluripotent stem cells, we hypothesized that due to its linkage with stemness, a feature important for many tumors, ZNF714 may also be implicated in tumor biology." (PMID 37958512, 2023). "Only active CD4+, effector memory T (Tem CD4+), type 2 T helper (Th2), and memory B lymphocytes positively correlated with ZNF714 level across various tumor types." (PMID 37958512, 2023). "We found that the ZNF714 mRNA level is significantly higher in 12 out of 24 tumor types compared to normal tissues, whereas lower ZNF714 expression was noted only in THCA." (PMID 37958512, 2023). "Our previous analysis of TCGA transcriptomic datasets identified ZNF714 as one of sixteen KRAB-ZNF genes commonly upregulated in many tumor types." (PMID 37958512, 2023). "We further inspected the correlation between ZNF714 expression and various aspects related to the interactions between the tumor and the immune system." (PMID 37958512, 2023). "Using GEPIA2 Similar Genes Detection mode, we downloaded the top 100 genes correlating with ZNF714 expression in all TCGA tumor types." (PMID 37958512, 2023). "ZNF714 mRNA level demonstrated a significant correlation with immune subtypes in 8 out 33 TCGA tumor types." (PMID 37958512, 2023). "Our previous study based on the TCGA transcriptomic profiling identified ZNF714 as one of the 16 KRAB-ZNF genes commonly overexpressed in many tumor types." (PMID 37958512, 2023). "These analyses, built upon our previous study, confirmed that ZNF714 mRNA levels are higher in many tumor types compared to normal samples." (PMID 37958512, 2023). "Mean expression of ZNF714 was similar in normal and tumor samples, whereas ZNF525, ZNF643, and ZNF707 fell below the detection level." (PMID 30444046, 2019). "Altogether, these data show that ZNF714 may affect the expression of various genes participating in many processes important for tumor biology." (PMID 37958512, 2023). "We also showed that ZNF714 expression correlates with tumor immunosuppressive features." (PMID 37958512, 2023). "Interestingly, several of those genes have documented tumor-suppressive functions, further supporting our in vitro results demonstrating an oncogenic role of ZNF714." (PMID 37958512, 2023). "Notably, CNV status positively correlated with ZNF714 expression in 14 out of 33 tumor types analyzed via the GSCA portal." (PMID 37958512, 2023). "First, we monitored ZNF714 mRNA expression in 24 types of normal and tumor tissues." (PMID 37958512, 2023). "We confirmed that ZNF714 is overexpressed in many tumor types." (PMID 37958512, 2023). "It would be interesting to test whether the tumors with high ZNF714 may benefit from anti-PD-L1 treatment or whether ZNF714 silencing may restore tumor immunogenicity leading to a decreased tumor expansion." (PMID 37958512, 2023). "In the current study, we aimed to test the hypothesis that ZNF714 plays an oncogenic role in tumor biology." (PMID 37958512, 2023). "Interestingly, ZNF714 expression showed a positive association with the expression of CD274, which is a gene coding for PD-L1, a checkpoint protein that blocks T cell activation, allowing the tumor to evade the immune system." (PMID 37958512, 2023). "In contrast, the correlation between ZNF714 expression and MHC genes, chemokines, and chemokine receptors revealed a tumor-specific pattern." (PMID 37958512, 2023).
tumor (continued). "Importantly, some the genes upregulated upon ZNF714 knockdown (PCDH20, STRA6, ARNT2, TIMP3) were previously shown to function as tumor suppressors." (PMID 37958512, 2023). "Third, ZNF714 expression showed a positive correlation with tumor stage and grade in LIHC and UCEC, which was not the case in any other tumor." (PMID 37958512, 2023).
ZNF714 also shares sentences with these, for which no sentence is quoted: metabolic disease (3 papers); cholangiocarcinoma (1); diabetes (1); head and neck cancer (1); mesothelioma (1); Obesity (1); paraganglioma (1); pheochromocytoma and (1); uveal melanoma (1).